LINC02881 (long independently transcribed non-coding RNA 2881)
Synonyms: formerly C10orf142
Gene: Long non-coding RNA gene on chromosome 10 (44,292,262 to 44,294,836, forward strand). Ensembl gene ENSG00000277288.
Diseases named in the same sentence as LINC02881 in open-access papers:
LINC02881 is named in the same sentence as 1 disease in open-access papers, as found by Europe PMC text mining. Sharing a sentence is not in itself a finding about the gene and the disease.
LINC02881 shares sentences with these, for which no sentence is quoted: macrosomia (1 paper).